NCOA4 (nuclear receptor coactivator 4)
Diseases named in the same sentence as NCOA4 in open-access papers (continued):
Sharing a sentence is not in itself a finding about the gene and the disease.
ovarian carcinoma (continued). "Overall, these data show that NCOA4 mRNA (NCOA4α and NCOA4β) as well as protein (NCOA4α) expression is increased in ovarian cancers relative to controls." (PMID 29435183, 2018). "Collectively, these results implicate the involvement of these factors in the functional responses of NCOA4 in ovarian cancer cells." (PMID 29435183, 2018). "Regulation of intracellular iron occurs via a ferritinophagic process involving NCOA4 (Nuclear Receptor Coactivator 4), represented by two major isoforms (NCOA4α and NCOA4β), whose contribution to ovarian cancer biology remains uninvestigated." (PMID 29435183, 2018). "The relationship between NCOA4 mutations and ovarian cancer has not yet been thoroughly investigated." (PMID 38509102, 2024). "For example, C-Myc amplified in ovarian cancer cells inhibits ferroptosis by inducing NCOA4-mediated ferritinophagy, but erastin selectively kills iron-addicted ovarian cancer cells by inducing ferroptosis and promoting NCOA4-mediated ferritinophagy and mitochondrial dysfunction." (PMID 37842240, 2023). "Ferritin autophagy and ferroptosis detection showed that C-MYC could inhibit ferroptosis through NCOA4-mediated ferritin autophagy, thus reducing ROS and inhibiting mitophagy in ovarian cancer cells." (PMID 36552889, 2022). "In vivo experiments showed that C-MYC could promote tumorigenesis and immune evasion in ovarian cancer cells through inhibiting HMGB1 release induced by NCOA4-mediated ferroptosis." (PMID 36552889, 2022). "Cell function tests showed that C-MYC could promote the proliferation and invasion of ovarian cancer cells through the NCOA4 axis." (PMID 36552889, 2022). "This experimental result confirmed that C-MYC might inhibit ferroptosis in ovarian cancer cells through NCOA4-mediated ferritin autophagy." (PMID 36552889, 2022). "The Western blot assay revealed that C-MYC could reduce HMGB1 release in ovarian cancer cells through the NCOA4 axis." (PMID 36552889, 2022). "In vitro and in vivo studies revealed that C-MYC could inhibit DAMP release and promote immune evasion in ovarian cancer through NCOA4-mediated ferritin autophagy and ferroptosis." (PMID 36552889, 2022). "Transwell assays revealed that compared with the NC group, the proportion of cells passing through the basement membrane was significantly increased in C-MYC-over-expressed ovarian cancer cells, while the cell proportion correspondingly decreased after NCOA4 over-expression in ovarian cancer cells." (PMID 36552889, 2022). "ROS detection showed that in C-MYC-up-regulated ovarian cancer cells, the ROS contents significantly decreased, while these changes could be reversed by NCOA4 over-expression." (PMID 36552889, 2022). "The results show that compared with the NC group, in C-MYC-over-expressed ovarian cancer cells, the red fluorescence intensity obviously increased, while these changes could be reversed through NCOA4 over-expression." (PMID 36552889, 2022). "Some scholars found that the abnormal expression of C-MYC in ovarian cancer cells could lead to significant changes in the expression level of NCOA4, as well as the content of ferritin and Fe2+." (PMID 36552889, 2022). "In general, the results of this study show that C-MYC was significantly up-regulated in ovarian cancer samples and could down-regulate NCOA4 expression through directly targeted binding." (PMID 36552889, 2022). "Ferritin autophagy and ferroptosis indicator assays showed that C-MYC could inhibit ferroptosis through NCOA4-mediated ferritin autophagy, thus inhibiting ROS accumulation and mitochondrial injury in ovarian cancer cells." (PMID 36552889, 2022). "Our research confirmed that NCOA4 over-expression could promote ferritin autophagy and ferroptosis in ovarian cancer cells, while NCOA4 inhibition could achieve the opposite results; all of these results further validated previous studies." (PMID 36552889, 2022).
ovarian carcinoma (continued). "Functional experiments confirmed that C-MYC could promote malignant phenotypes in ovarian cancer cells through the NCOA4 axis." (PMID 36552889, 2022). "Some researchers found that the abnormal expression of C-MYC could lead to obvious changes in ferritin and Fe2+ content in ovarian cancer cells, while they also found that these changes were significantly correlated with NCOA4 expression." (PMID 36552889, 2022). "Collectively, our results implicate NCOA4 in ovarian cancer biology in which it could be involved in the transition from precursors to OVCA." (PMID 29435183, 2018). "NcoA4 mRNA and protein is also expressed in human ovarian cancer cell lines." (PMID 22562579, 2012). "Therefore, we speculate that C-MYC may affect ferritin autophagy by regulating NCOA4 expression, thus participating in the ferroptosis of ovarian cancer cells." (PMID 36552889, 2022). "Thus, we demonstrated that C-MYC could inhibit mitophagy in ovarian cancer cells through the NCOA4 axis." (PMID 36552889, 2022). "Thus, we concluded that C-MYC could maintain the stability of mitochondrial membrane potential in ovarian cancer cells through the NCOA4 axis." (PMID 36552889, 2022). "Thus, we inferred that NCOA4 may play a key role in the progression of ovarian cancer, which was consistent with the results of previous studies." (PMID 36552889, 2022). "Therefore, we speculated that C-MYC may affect ferritin autophagy by regulating the expression of NCOA4 and then participate in the process of ferroptosis in ovarian cancer cells." (PMID 36552889, 2022). "By blocking nuclear receptor coactivator 4 (NCOA4)-mediated ferritin autophagy, MYC prevents ovarian cancer cells from ferroptosis." (PMID 40290126, 2025). "In ovarian cancer, studies have investigated the expression levels of C-MYC and NCOA4 and their relationship with cancer malignancy." (PMID 39403142, 2024). "Western blot assays revealed that in C-MYC-over-expressed ovarian cancer cells, extracellular free HMGB1 content significantly decreased, while NCOA4 up-regulation could reverse this change." (PMID 36552889, 2022). "The binding site and regulatory mechanisms of the C-MYC/NCOA4 axis in ovarian cancer cells have not been fully clarified; we plan to expound on this point through exploration of the molecular mechanisms of NCOA4 mRNA transcription in the future." (PMID 36552889, 2022). "Herein, we have defined that NCOA4 is elevated in transformed endometriotic cells (relative to non-transformed cells), in malignant ovarian cancer cells and in a subset of ovarian tumors." (PMID 29435183, 2018). "First, we detected co-localization of ferritin and lysosome labels, and the results show that the co-localization of NCOA4 and lysosome (LAMP2) was significantly inhibited in C-MYC-over-expressed ovarian cancer cells, while NCOA4 up-regulation could reverse this change." (PMID 36552889, 2022). "Thus far, there is only limited data describing increased NCOA4 transcripts in ovarian carcinomas; thus, the contribution of NCOA4 to the progression of OVCA has not yet been thoroughly investigated." (PMID 29435183, 2018).
glioma (13 papers, 2019 to 2025). A benign or malignant brain and spinal cord tumor that arises from glial cells (astrocytes, oligodendrocytes, ependymal cells). "Overexpression and knockdown of NCOA4 were induced in glioma cell lines via transduction of recombinant adenovirus encoding NCOA4 and NCOA4 siRNA, respectively." (PMID 40794264, 2025). "In glioma, a study reported that NCOA4 caused degradation of ferritin and a subsequent increase in levels of Fe2+and ultimately ferroptosis." (PMID 35281049, 2022). "To preliminarily explore the mechanism underlying aberrant NCOA4 expression in glioma, we investigated the relationship between NCOA4 expression and DNA methylation; an obvious negative correlation (r = − 0.282, P < 0.01) between NCOA4 expression and NCOA4 DNA methylation was observed." (PMID 40794264, 2025). "In this study, NCOA4 was shown to repress glioma progression partially through inhibiting the SHH pathway." (PMID 40794264, 2025). "The NCOA4 expression level was significantly lower in glioma tissues than in normal brain tissues in the training set." (PMID 40794264, 2025). "WB and IHC revealed that NCOA4 was markedly downregulated in glioma cell lines and human specimens compared to controls, and high NCOA4 expression was associated with a better glioma prognosis." (PMID 40794264, 2025). "Knockdown of PTCH1 partially reversed the inhibitory effects of NCOA4 on GBM cell growth and invasion, suggesting that PTCH1, a potential downstream gene of NCOA4, is involved in the suppressive effect of NCOA4 on glioma development." (PMID 40794264, 2025). "In summary, bioinformatics analysis and our experiments revealed that NCOA4 expression is downregulated in gliomas and is negatively correlated with glioma grade." (PMID 40794264, 2025). "PTCH1 knockdown reversed the inhibitory effects of NCOA4 on the malignant behaviours of glioma cells." (PMID 40794264, 2025). "NCOA4 overexpression inhibited glioma cell growth and invasion and induced apoptosis, whereas NCOA4 knockdown promoted glioma cell growth." (PMID 40794264, 2025). "Mechanistically, NCOA4 overexpression inhibits the progression of glioma by suppressing the SHH pathway." (PMID 40794264, 2025). "While the proliferation and invasion of glioma cells were promoted, apoptosis was inhibited when NCOA4 was knocked down." (PMID 40794264, 2025). "NCOA4 overexpression inhibited tumour cell proliferation and invasion and induced glioma cell apoptosis, whereas NCOA4 knockdown promoted glioma cell growth and invasion and suppressed apoptosis." (PMID 40794264, 2025). "The apoptosis indices of 23N and U87 cells transfected with siR-NCOA4 were decreased, and NCOA4 knockdown suppressed glioma cell apoptosis." (PMID 40794264, 2025). "In this study, we assessed the expression of NCOA4 in gliomas and the effect of NCOA4 on the proliferation of glioma cells and explored the mechanisms by which NCOA4 affects glioma progression." (PMID 40794264, 2025). "NCOA4 expression was downregulated in glioma samples compared with AN tissues and was negatively correlated with tumour grade." (PMID 40794264, 2025). "We further analysed the correlation of the NCOA4 expression level of glioma samples from the tissue chip with tumour grade and patient OS, sex and age." (PMID 40794264, 2025). "The NCOA4 expression level was negatively correlated with the grade of glioma, and patients with positive NCOA4 staining had longer survival than those with negative NCOA4 staining." (PMID 40794264, 2025). "NCOA4 expression was downregulated in most glioma cell lines compared with astrocytes; it was significantly decreased in LN229, TJ905, A172, T98G, U251 and SNB19 cell lines and slightly decreased in 23N, U87, LN18 and B2-17 cell lines." (PMID 40794264, 2025). "Together, these results suggest that ferritinophagy-mediated alterations in ferritin and NCOA4 level increase the labile iron pool, leading to ferroptosis in glioma cells." (PMID 38886572, 2024).
glioma (continued). "Remarkably, both pharmacological (BafA1) and genetic (shAtg-5 and shAtg-7) inhibition of autophagy significantly diminished RSL3-induced FTH1 and NCOA4 degradation, indicating that autophagy mediates ferritin degradation in glioma cells during ferroptosis." (PMID 38886572, 2024). "Consistent with the previous reports, RSL3, and erastin induced the time-dependent degradation of FTH1 and NCOA4 in glioma cells." (PMID 38886572, 2024). "Pre-treatment with ROS scavengers N-acetylcysteine (NAC) and Trolox (6-hydroxy-2,5,7,8-tetramethylchromane-2-carboxylic acid) attenuated RSL3-induced Par-4 induction, LC3-II conversion, and p62/SQSTM1, FTH1, and NCOA4 degradation in glioma cells." (PMID 38886572, 2024). "Tumor suppression by inducing NCOA4-mediated ferroptosis has been shown to be feasible in a variety of tumors, including gliomas." (PMID 38049396, 2023). "More importantly, we explore and demonstrate the role and mechanism of the HECW1/ZNF350/NCOA4 pathway in regulating ferroptosis and identify new molecular targets for glioma therapy." (PMID 38049396, 2023). "Taken together, we confirmed that HECW1, ZNF350, and NCOA4 form an integral pathway involved in the regulation of ferroptosis in gliomas." (PMID 38049396, 2023). "In the study, we found that HECW1 blocked the progression of glioma cells and enhances iron accumulation and lipid peroxidation (LPO), which is caused by inducing NCOA4-mediated ferroptosis." (PMID 38049396, 2023). "WB analysis revealed that only NCOA4 protein expression was significantly altered in HECW1-silenced glioma cells." (PMID 38049396, 2023). "NCOA4 is a selective cargo receptor for the autophagic degradation of ferritin in glioma which is known as ferritinophagy." (PMID 35359663, 2022). "Moreover, glioma patients with higher NCOA4 expression exhibit longer OS, and NCOA4 suppresses glioma progression through the SHH pathway." (PMID 40794264, 2025). "Moreover, analyses of Kaplan–Meier curves revealed glioma patients with high expression and low methylation of NCOA4 had better overall survival (OS) than those with low expression and high methylation of NCOA4 (P < 0.01)." (PMID 40794264, 2025). "NCOA4 hypomethylation and high expression also predicted better OS in glioma patients." (PMID 40794264, 2025). "The expression of NCOA4 was further detected in glioma cells and specimens by WB and IHC." (PMID 40794264, 2025). "We further assessed the expression of NCOA4 in glioma cell lines and specimens by WB and IHC." (PMID 40794264, 2025). "To investigate whether NCOA4 exerts its inhibitory effect on glioma cell growth via the SHH pathway through the regulation of PTCH1, we knocked down PTCH1 in NCOA4-overexpressing GBM cells by transfecting them with siRNA-PTCH1." (PMID 40794264, 2025). "NCOA4 silencing largely counteracts the toxicity of ferroptosis inducers to glioma cells." (PMID 38049396, 2023). "Also, the protein expression level of NCOA4 was increased in MXRA8 knockdown glioma cells, while FTH1 was reduced." (PMID 35281049, 2022). "Next, we examined whether NCOA4 acts as a tumor suppressor in gliomas by eliciting ferroptosis." (PMID 38049396, 2023). "Therefore, we conclude that NCOA4 acts as a driver of ferroptosis in glioma cells." (PMID 38049396, 2023). "Thus, the COPZ1/NCOA4/FTH1 axis may be a novel therapeutic target in the treatment of gliomas." (PMID 33420375, 2021). "We discovered for the first time that NCOA4 can regulate glioma progression through the SHH pathway, not just by mediating ferroptosis." (PMID 40794264, 2025). "In this study, a negative correlation between NCOA4 expression and methylation was observed in glioma samples." (PMID 40794264, 2025). "NCOA4 expression was downregulated in glioma cell lines and specimens compared with nontumorous brain tissues and was negatively correlated with glioma grade." (PMID 40794264, 2025). "We assessed the expression of NCOA4 in 6 glioma samples and adjacent nontumorous (AN) brain tissues by WB." (PMID 40794264, 2025).
glioma (continued). "Furthermore, consistent with glioma cells, double knockout Par-4−/− MEFs also significantly inhibited RSL3 or ML210-induced degradation of FTH1 and NCOA4." (PMID 38886572, 2024). "Compared with that in the negative control group, the growth of glioma cells in the NCOA4 overexpression group was greatly inhibited, whereas cell death was notably increased." (PMID 38049396, 2023). "Likewise, our study also demonstrated that inhibition of MXRA8 increased the protein expression of NCOA4 and decreased FTH1 protein levels in glioma cells." (PMID 35281049, 2022). "Here, we demonstrated the regulatory mechanism of the HECW1/ZNF350/NCOA4 pathway on ferroptosis in gliomas, which might provide a novel strategy for glioma treatment." (PMID 38049396, 2023). "However, the regulatory mechanism of ferroptosis induced by NCOA4 in glioma has not been studied deeply." (PMID 38049396, 2023). "However, there is no relevant research indicating whether NCOA4 can regulate the progression of glioma through pathways other than ferroptosis." (PMID 40794264, 2025).
Sepsis (13 papers, 2022 to 2026). Sepsis is defined as life-threatening organ dysfunction caused by a dysregulated host response to infection. "During sepsis, infection induces upregulation of nuclear receptor coactivator 4 (NCOA4), which mediates selective ferritin autophagy, resulting in Fe3+ release and iron-dependent cell death." (PMID 40364841, 2025). "YAP1 disrupted the NCOA4–FTH1 reaction and inhibited NCOA4-mediated ferritinophagy to prevent ferroptosis and subsequent mitochondrial ROS-related dysfunction in sepsis-induced ALI." (PMID 39161900, 2024). "Animal studies have shown that in IRI-AKI, STING promotes ferroptosis through NCOA4-dependent ferritinophagy, and inhibiting ferroptosis can alleviate drug or sepsis-induced kidney injury." (PMID 39308866, 2024). "Notably, NFKBIA (encoding IκBα) shows infection-dependent upregulation in SARS-CoV-2 infections, and extracellular NCOA4 exacerbates inflammatory responses through NF-κB activation in sepsis." (PMID 41557688, 2026). "In sepsis, LPS increased NCOA4 expression and intracellular Fe2+ levels." (PMID 39355841, 2024). "Nevertheless, the connection between NCOA4-mediated ferritinophagy and sepsis-induced ALI remains unclear." (PMID 35979359, 2022). "Taken together, these experimental data suggested that YAP1 could suppress FTH1 autophagic degradation mediated by NCOA4, which was crucial for protecting pulmonary epithelial cells from sepsis-induced ferroptosis." (PMID 35979359, 2022). "Herein, we first reported that STING could trigger ferroptosis by directly increasing the level of intracellular iron, which is dependent on NCOA4-mediated ferritin degradation, leading to sepsis-related organ damage." (PMID 35902564, 2022). "However, during sepsis, infection stimulates the upregulation of nuclear receptor coactivator 4 (NCOA4), which specifically recognizes ferritin, initiating ferritin autophagy, releasing a large amount of Fe3+, elevating intracellular free iron concentration, and promoting iron-dependent cell death." (PMID 39252831, 2024). "Our findings uncover a novel mechanism by which the interaction between STING and NCOA4 regulates innate immune response and ferroptosis, which can be reversed by HET0016, providing mechanistic and promising targets insights into sepsis." (PMID 35902564, 2022). "Mir22hg silencing lightened ferroptosis and ferritinophagy in LPS-induced MLE-12 cells and sepsis mouse models, as presented by the downregulated MDA, ROS, Fe2+, NCOA4, and SLC3A2 levels, upregulated GPX4, GSH, and FTH1 levels, along with a decrease in autophagy." (PMID 38842666, 2024). "Moreover, it was pointed out that lipopolysaccharide increased NCOA4 expression and intracellular Fe2+ level but reduced ferritin level, ultimately inducing ferroptosis, and targeting ferroptosis induced by ferritinophagy might prevent sepsis-induced cardiac damage." (PMID 37522124, 2023). "In summary, we propose a novel paradigm that has never been previously reported, in which the interaction between STING and NCOA4 is central to the pathogenesis of sepsis and highlights the importance of targeting non-IFN-mediated pathway injury regulated by STING for the treatment of sepsis." (PMID 35902564, 2022). "Although we demonstrated that STING directly induces ferroptosis in a manner dependent on its interaction with NCOA4 but independent of cGAS or TBK1 in lethal sepsis, whether the role of STING upon iron metabolism orchestrates immune homeostasis still requires further investigation." (PMID 35902564, 2022).